SMIM22 (small integral membrane protein 22)
Description:
May modulate lipid droplet formation throught interaction with SQLE.
Synonyms: CASIMO1
Tractability: Antibody: UniProt predicts a signal peptide or a membrane-spanning region.
Gene: Protein-coding gene on chromosome 16 (4,788,397 to 4,796,731, forward strand). Ensembl gene ENSG00000267795.
Subcellular location: Membrane; Late endosome
Subcellular location (Human Protein Atlas): Nucleoplasm; Cytosol
Gene Ontology:
Molecular function: protein binding
Biological process: lipid droplet formation; positive regulation of cell migration; regulation of actin cytoskeleton organization; regulation of cell cycle; regulation of cell population proliferation
Cellular component: late endosome; membrane
Genetic constraint (gnomAD): Loss-of-function variants: 18 observed, 8.55 expected, observed/expected ratio (o/e) 2.11. That is too few expected variants to judge how well the gene tolerates losing a copy. Missense variants: 159 observed, 106.79 expected, observed/expected ratio (o/e) 1.49, 90% interval 1.31 to 1.7. Synonymous variants: 67 observed, 45.89 expected, observed/expected ratio (o/e) 1.46, 90% interval 1.2 to 1.78.
Homologues: Orthologues: chimpanzee SMIM22 (100% identical), macaque SMIM22 (90% identical), rabbit SMIM22 (78% identical), guinea pig SMIM22 (69% identical), mouse Smim22 (68% identical), rat Smim22 (64% identical), pig SMIM22 (61% identical), dog SMIM22 (59% identical), zebrafish si:ch1073-443f11.2 (36% identical).
Diseases named in the same sentence as SMIM22 in open-access papers:
SMIM22 is named in the same sentence as 10 diseases in open-access papers, as found by Europe PMC text mining. Sharing a sentence is not in itself a finding about the gene and the disease. The quoted sentences say what the papers report.
breast cancer (12 papers, 2021 to 2025). A primary or metastatic malignant neoplasm involving the breast. "SMIM22 also called CASIMO1 is a critical factor for proliferation and cell cycle progression in breast cancer." (PMID 37122696, 2023). "In breast cancer, Linc00908 translates the protein SMIM30 (also called ASRSP) and CASIMO1 encodes the protein SMIM22, whereas in colon cancer, Loc90024 encodes the SRSP protein and HOXB-AS3 translates the homonym protein." (PMID 35004666, 2021).
cancer (5 papers, 2020 to 2025). A tumor composed of atypical neoplastic, often pleomorphic cells that invade other tissues. "In these contexts, SMIM22 has been shown to enhance tumor cell proliferation, supporting a potential dual role in both metabolic regulation and cancer progression." (PMID 40558487, 2025). "Small integral membrane protein 22 (SMIM22, Gene ID: ENSG00000267795) is a newly discovered gene associated with cancer development." (PMID 39215037, 2024). "While SMIM22 has been primarily studied in the context of cancer tumorigenesis, recent research suggests that it may also contribute to lipid metabolism." (PMID 40558487, 2025). "Although the mechanisms by which SMIM22 regulates lipid biogenesis remain unclear, its upregulation in cancers such as non-small-cell lung cancer and hepatocellular carcinoma raises the possibility that it may contribute to tumor progression through effects on lipid metabolism." (PMID 40558487, 2025).
SMIM22 also shares sentences with these, for which no sentence is quoted: tumor (4 papers); colon cancer (2); breast tumors (1); hepatocellular carcinoma (1); infection (1); liver fibrosis (1); lung carcinoma (1); small cell lung carcinoma (1).